MACORIS (macrophage enriched lincRNA repressor of IFN-gamma signaling)
Gene: Long non-coding RNA gene on chromosome 10 (31,649,410 to 31,707,699, reverse strand). Ensembl gene ENSG00000237797.
Diseases named in the same sentence as MACORIS in open-access papers:
MACORIS is named in the same sentence as 1 disease in open-access papers, as found by Europe PMC text mining. Sharing a sentence is not in itself a finding about the gene and the disease. The quoted sentences say what the papers report.
tumor (2 papers, 2022). "In contrast, the expression levels of AC104819.3 and MACORIS in the tumor tissue were significantly lower than those in the adjacent normal tissue." (PMID 36185235, 2022). "Only four lncRNAs (LCMT1-AS1, MACORIS, MYOSLID, and ZEB1-AS1) were tested in the CC adjacent tissues and tumor tissues using qRT–PCR." (PMID 35237659, 2022). "Besides, the expression levels of AC104819.3 and MACORIS in tumor tissues were significantly lower than those in adjacent normal tissues." (PMID 36185235, 2022).